INS (insulin)
Diseases named in the same sentence as INS in open-access papers (continued):
Sharing a sentence is not in itself a finding about the gene and the disease.
diabetes (continued). "At present, researchers believe that increased insulin secretion usually occurs before insulin resistance and play an important role in the progression of diabetes." (PMID 37830511, 2023). "The study included 69 insulin-treated diabetes individuals were compared to 36 non-insulin treated diabetes individuals attending the diabetes clinic at the Mekelle Hospital in Ethiopia." (PMID 36778553, 2023). "Traditional nutrition recommendations given to patients with diabetes focus on carbohydrate counting and suggest the consumption of an unrestricted diet where the low endogenous insulin production is compensated by an external insulin supply." (PMID 37584373, 2023). "Current diabetes treatments work by boosting pancreatic insulin production, among other glycemic control strategies, decreasing intestine absorption, increasing insulin receptor sensitivity, and reducing hepatic gluconeogenesis." (PMID 37842332, 2023). "Since insulin was discovered by Canadians F.G. Banting and C.H. Best in 1921, it has been widely used in the clinical treatment of diabetes mellitus for the past 100 years." (PMID 37376294, 2023). "Diabetes is a group of metabolic diseases characterized by chronic hyperglycemia resulting from impaired insulin secretion and/or action." (PMID 36979645, 2023). "Approximately one third of Chinese patients with diabetes use insulin for antihyperglycemic treatment, of whom 26.7% use BI alone and 13.4% use BI combined with prandial insulin." (PMID 37864379, 2023). "Diabetes mellitus is a heterogeneous metabolic disorder characterized by chronic hyperglycemia due to impaired insulin secretion, defective insulin action, or both." (PMID 37441190, 2023). "Few studies have reported the adherence to and efficacy of continuous glucose monitoring (CGM) for improving diabetes management in insulin-treated older adults with type 2 diabetes mellitus (T2DM)." (PMID 37993898, 2023). "The conventional treatment of diabetes includes diet modification, increased physical activity, oral hypoglycemic drugs, and insulin therapy." (PMID 37371552, 2023). "From these various reviews, the risk factors for BPH include (a) age, (b) smoking (vaping), (c) obesity/overweight, (d) ↑ insulin, (e) ↑ lipids, (f) diabetes, (g) hypertension, and (h) depression." (PMID 36982560, 2023). "Due to their higher rate of proliferation and insulin production, rodent cell lines were more routinely used in pancreas and diabetes research than human cell lines." (PMID 36960965, 2023). "A common way to diagnose diabetes consists of measuring the function of beta cells through glucose metabolism indicators such as plasma glucose, glycated hemoglobin (HbA1c), insulin or its byproduct C-peptide." (PMID 36839820, 2023). "So, the IoMT makes it possible for the device to collect a sizable amount of data that can be examined to optimize the controller that give diabetes patients appropriate amount of insulin." (PMID 37667042, 2023). "“Guidelines for Diabetes Drug Injection Technology in China (2016 Edition)” recommends the use of needle-free syringes for insulin therapy in diabetic patients." (PMID 36864833, 2023). "The only evidence of a possible positive correlation between insulin use and thyroid cancer comes from a 2011 study analyzing data from the Danish National Diabetes Register and Cancer Registry." (PMID 38146457, 2023). "The longtime glucose and insulin dynamics depicted by the model are in good agreement with the clinical observations of diabetes progression." (PMID 36848379, 2023). "We intend to analyze the genes related to the DB, IR, and IS possibilities regarding the insulin–diabetes binomial." (PMID 38136941, 2023). "The proportion of patients treated with insulin was higher in the diabetes duration ≥ 5 years group than in the < 5 years group (8.03% vs. 3.63%)." (PMID 37208706, 2023).
diabetes (continued). "For example, for the effective uptake of glucose, cells need to be co-stimulated with insulin, and in diabetes the reduction in the release of insulin can lead to starvation of cells in an otherwise nutrient-full environment." (PMID 37386259, 2023). "↑Serum insulin level, Th2-bias ed. cytokine response; ↓Onset and the development of diabetes, Th1 pro-inflammatory cytokines levels, MHC class II and CD86, TLR4 and downstream molecules’ expression in the pancreas." (PMID 37396125, 2023). "Following the completion of the 28-day treatment regimen, the mice with diabetes mellitus exhibited a significant decrease in blood insulin levels in comparison to the control group of mice with normal physiological conditions (p < 0.05)." (PMID 37836618, 2023). "Diabetes mellitus was present in 16 (34.8%) of our patients, and at the same time, all the patients had received insulin therapy." (PMID 36900737, 2023). "It has been reported that exercise or restriction of energy intake enhances skeletal muscle mitochondrial levels and oxidase activity, reduces body weight, and improves insulin sensitivity in patients with obesity and diabetes." (PMID 37900128, 2023). "Diabetes has been effectively managed with insulin since it was discovered in the 1920s by Banting and Best." (PMID 37143729, 2023). "Metabolic factors such as a high-fat diet, obesity, and diabetes mellitus are closely related to insulin resistance and hyperinsulinemia, which increase the expression of insulin and insulin-like growth factor-1." (PMID 37637156, 2023). "Limited resource setting needs to bridge the gap on family involvement to improve the diabetes care beyond insulin supply and blood glucose monitoring." (PMID 37033222, 2023). "The study demonstrated marked glycemic benefits after switching the basal insulin of uncontrolled patients with diabetes (mean HbA1c of 9%) to insulin dugledac after a 90-day follow-up period." (PMID 36601214, 2023). "The simulated dynamics of the obesity-diabetes model delineate the long-term impact of obesity on the trends of glucose and insulin levels." (PMID 36848379, 2023). "The data was stratified according to the age, gender, duration of diabetes, duration of insulin use, frequency of LH and duration since last instructions reviewed." (PMID 36694770, 2023). "In conclusion, this study sheds light on the multifaceted landscape surrounding the adoption of wearable insulin biosensors among individuals managing diabetes." (PMID 38239544, 2023). "Diabetes is a chronic metabolic disease that lasts a lifetime, especially type I diabetes, which requires frequent subcutaneous injections of insulin (INS) to maintain blood glucose balance." (PMID 36986680, 2023). "There are two major types of diabetes: type 1 diabetes (T1D) is distinguished by insufficient levels of insulin while type 2 diabetes (T2D) is characterized by the ineffective use of insulin by cells." (PMID 36839596, 2023). "This exhibited a further reduction at the six-month follow-up in addition to a positive reflection in insulin sensitivity, indicating successful control of diabetes among study participants." (PMID 38022144, 2023). "This work addresses the limitations of existing ML/DL methods (Section 2.1.1) for predicting glucose profiles by developing models using a dataset of diverse individuals with insulin-requiring diabetes who use open-source AID systems." (PMID 36981436, 2023). "Autologous diabetes cell therapy using patient-specific iPSC-islets, which contain the missing insulin-secreting β-cells, has the potential to eliminate the need for post-transplant immunosuppression." (PMID 38203514, 2023). "The approach regarding diabetes technology use is reminiscent of the earlier literature on intensive insulin therapy from the DCCT." (PMID 37794113, 2023).
diabetes (continued). "Type 2 diabetes mellitus (T2DM) accounts for over 90% of all patients with diabetes and is characterized mainly by insulin resistance, reduction of insulin secretion, and hyperglycemia." (PMID 36768777, 2023). "Diabetes mellitus, more simply called diabetes, manifests as continuous hyperglycemia because any or enough of the insulin cannot be made in the pancreas or efficiently used by the body; it is a severe and common chronic disease." (PMID 37964315, 2023). "Altered insulin secretion and action are major contributors to the pathogenesis of diabetes mellitus (DM)." (PMID 37241071, 2023). "Diabetes results from failure of pancreatic β cells to secrete sufficient insulin to regulate glucose homeostasis." (PMID 38032734, 2023). "For example, in a recent review on health-related QoL in children with diabetes using insulin infusion systems, Rosner and Roman-Urrestarazu identified eight different instruments across the 15 included studies." (PMID 40303260, 2023). "Even prior to regulatory approval, these devices have assisted many people with diabetes in their day-to-day decision-making on insulin dosing and provide the foundations for advanced diabetes technologies that tie insulin dosing to sensor glucose levels." (PMID 37794113, 2023). "New facts about insulin", in which he claimed his priority right on the discovery of Acomatol, a preparation that was successfully used to treat severe forms of diabetes, including coma, years ahead of insulin." (PMID 36585966, 2023). "Diabetes mellitus (DM) is a metabolic disorder characterized by chronic high blood sugar levels that occur due to insulin dysfunction and impaired secretion, which are responsible for processing carbohydrates, proteins, and fats." (PMID 38292989, 2023). "Type 2 diabetes mellitus is characterized by varying degrees of insulin resistance, impaired insulin secretion, and increased hepatic glucose production." (PMID 36979649, 2023). "In turn, diabetes is conceived as a chronic disease related to high levels of circulating glucose as a result of the body being unable to effectively use the insulin that it produces." (PMID 37103278, 2023). "The massive and fast decline of insulin levels leads to the upsurge of glucose and transitions the patient to overt diabetes in the end." (PMID 36848379, 2023). "Diabetes is a chronic metabolic disorder that occurs due to impaired secretion of insulin, insulin resistance, or both." (PMID 37970376, 2023). "The guidelines set forth by the Diabetes in Pregnancy study Group India (DIPSI) recommend insulin as the first line of treatment for GDM in cases where diet alone is not sufficient (nhm.gov.in; last accessed: 29 July 2023)." (PMID 37765126, 2023). "GDM is typically diagnosed later in pregnancy, resulting in a shorter duration of insulin treatment compared to other forms of diabetes." (PMID 37510687, 2023). "In type 2 diabetes mellitus, 400 mg daily dose of G. sylvestre aqueous extract lowers the HbA1C level while significantly decreased the insulin demands." (PMID 38107140, 2023). "Hypoglycemia is very common in people with diabetes, especially those with insulin-treated diabetes." (PMID 37887414, 2023). "Various modes of intermittent fasting decrease body weight and lowered diabetes parameters such as fasting glucose and insulin, HOMA-IR index, and glycosylated hemoglobin (HbA1c)." (PMID 38201865, 2023). "Insulin resistance (IR) is a state of decreased sensitivity and responsiveness to insulin concentrations that occurs before a person is diagnosed with type 2 diabetes mellitus (T2DM)." (PMID 37693717, 2023). "We identified six different clinical scenarios, including type 1 diabetes, type 2 diabetes, pregnancy on intensive insulin therapy, regular physical exercise, new onset of diabetes, and frailty." (PMID 37676398, 2023).
diabetes (continued). "Metabolic actions of HN comprise improved blood glucose and insulin sensitivity, as well as enhanced glucose transporter type 4 expression in rodent models of diabetes, highlighting its potential as therapeutic targets in metabolic diseases." (PMID 36642986, 2023). "Diabetes mellitus is a complex disorder characterized by insufficient insulin production or insulin resistance, which results in a lifelong dependence on glucose-lowering drugs for almost all patients." (PMID 36904097, 2023). "This accumulation is caused by decreased substrate oxidation levels, which further exacerbates diabetes by inhibiting insulin signaling." (PMID 37900128, 2023). "Homeostasis model assessment is typically used in type 2 diabetes mellitus as index to measure the sensitivity of the insulin to its receptor and as well as viability and availability of beta cells that are responsible for synthesizing insulin." (PMID 38035005, 2023). "Although insulin treatment has long been the basis of glucose control in diabetes, previous observational studies have suggested a possible correlation between insulin therapy and increased cardiovascular events." (PMID 37528628, 2023). "We found that phospho-PPAR-γ levels were significantly higher in the EXE and EMC groups than in the PRE group, suggesting that combined therapy and exercise alone can improve insulin sensitivity and diabetes by targeting the PPAR-γ-signaling pathway." (PMID 37899436, 2023). "Patients that were 35 years and older, female, employed, had a high body mass index, were on oral hypoglycaemic and/or insulin in combination, and receiving treatment longer than 3 years, had an increased odd of uncontrolled diabetes." (PMID 38974271, 2023). "Encapsulation of insulin in a matrix of zinc-silica for the safe and intended release of drugs is one of the procedures for the therapeutic treatment of diabetes." (PMID 37388336, 2023). "Diabetes, which mainly affects adults, frequently results in high blood glucose levels because of insufficient insulin synthesis and insulin resistance (IR)." (PMID 37834439, 2023). "In conclusion, dulaglutide combined with insulin degludec can significantly reduce overall glucose fluctuations and appetite early in diabetes patients, resulting in a higher TIR." (PMID 37255975, 2023). "Following surgical excision, both insulin sensitivity and insulin secretion improves, and in 23–58% of patients with pre-existing diabetes, glucose metabolism returns to normal." (PMID 37628857, 2023). "Diabetes can present a particular challenge in the management of suicidal ideations and behaviours given that insulin, the essential treatment for type one diabetes (and used by many individuals with type 2 diabetes) is potentially lethal in overdose." (PMID 37840692, 2023). "This calculator uses simple characteristics such as age at diagnosis, sex, time to insulin treatment, glucose lowering treatment, body mass index (BMI), HbA1c and family history of diabetes." (PMID 37033247, 2023). "In 2016, the Afghan Ministry of Public Health, in collaboration with WHO, estimated that 8.4% of Afghans were living with diabetes, predominantly non-insulin dependent." (PMID 37667247, 2023). "Inflammation of the islets of Langerhans leads to the destruction of pancreatic beta cells, and diabetes develops violently: mice lose weight quickly and require insulin administration." (PMID 36829539, 2023). "Type I diabetes, which is insulin-dependent, and type II diabetes, which is insulin-independent, are the two main types of diabetes." (PMID 36974247, 2023). "Selective antagonism of SSTR2 has been shown in various non-clinical models of T1D and in early phase clinical trials to at least partially restore glucagon counterregulation, with the goal of reducing hypoglycemia exposure in insulin-requiring diabetes." (PMID 38298268, 2023).
diabetes (continued). "A study of human pancreatic islets showed that three out of four type 2 diabetes mellitus patients had decreased β-cell mass and insulin expression." (PMID 36614256, 2023). "Insulin is indicated for patients with severe hyperglycemia (random glucose >300 mg/dL), symptomatic diabetes, ketoacidosis, acute medical events, concomitant diseases, admission, and inability to take oral antidiabetic drugs." (PMID 37242426, 2023). "Simultaneous electrophysiologic and glucose monitoring is rarely performed in clinical practice and the induction of severe hypoglycemia in individuals with insulin-treated diabetes is dangerous and unethical." (PMID 37200277, 2023). "Among the natural agonists of PPARγ are the polyunsaturated fatty acids, glucocorticoids, and insulin, with thiazolidinedione also having a high affinity for PPARγ, which exercise their therapeutic effects in type 2 diabetes mellitus." (PMID 36986146, 2023). "Our findings further expose that although insulin syringes are labeled single-use only; health workers in Malawi provide “unofficial” guidelines advising patients living with diabetes to reuse insulin syringes and needles due to a scarcity of resources." (PMID 37828591, 2023). "Co-morbidities, such as diabetes made the diet even more difficult to manage.“I was diagnosed with diabetes about 10 years ago and I’m on insulin." (PMID 37817256, 2023). "Insulin restrictors had significantly higher HbA1c (9.2 ± 2.2; p < 0.001), later onset of diabetes (11.6 ± 4.5; p = 0.041), and significantly higher DEPS-R scores (24.8 ± 10.4; p < 0.001)." (PMID 36837546, 2023). "These insights into pancreatic TRPC3 function are considered as an essential step toward a better understanding of the intricate insulin secretion physiology and pave the way for the development of promising diabetes‐focused treatments." (PMID 36642838, 2023). "Diabetes mellitus (DM) is a chronic endocrine and metabolic disorder that is characterized by elevated blood glucose level generally referred to as hyperglycemia and it is due to deficiency in insulin secretion or action." (PMID 37055870, 2023). "The present study showed that a variant associated with the high end of the z-insulin spectrum (rs2122859) was located on the SLC28A1 gene, which has been shown to be associated with both diabetes and late-onset Alzheimer’s disease." (PMID 37420130, 2023). "Less common forms include gestational diabetes (where hormones block the efficient use of insulin) and monogenic diabetes." (PMID 38229904, 2023). "This is also reflected in the different medications predominantly taken by patients with either type 1 or type 2 diabetes, as there is a higher prevalence of DD in patients with diabetes taking metformin compared to patients with diabetes taking insulin." (PMID 37443309, 2023). "This is an insulin-producing pancreatic islet cell line and is therefore considered suitable for research on diabetes." (PMID 37373436, 2023). "At the age of 10, because fasting blood glucose was 16.0 mmol/L, the patient was diagnosed with “type 1 diabetes mellitus” and treated with insulin." (PMID 37974252, 2023). "Insulin secretion, action, or a combination of both is compromised in diabetes mellitus (DM), a metabolic disorder." (PMID 37842332, 2023). "Clinicians who use CDSSs as smartphone apps were more likely to change their diagnoses and treatments to more appropriate ones; for example, they were more likely to start early insulin therapy for patients with diabetes." (PMID 37379066, 2023). "A subset of children undergoing TPIAT will develop postpancreatectomy diabetes and require chronic insulin therapy." (PMID 40303247, 2023). "Multiple daily injections via subcutaneous route are the primary modes of insulin delivery for patients with Diabetes Mellitus." (PMID 36839674, 2023).